ACVR2A (activin A receptor type 2A)
Diseases named in the same sentence as ACVR2A in open-access papers (continued):
Sharing a sentence is not in itself a finding about the gene and the disease.
tumor (continued). "In order to study the role of EGF-CFC family molecules in NB tumor sphere formation, the expression levels of CFC1, TDGF1, ACVR2A, ACVR2B, and ACVR1B were measured using a microarray." (PMID 28620148, 2017). "ACVR2A, TGFBR2, KIAA2018, ASTE1 and SLC22A9 frequently harbour MSI events in STAD and COAD, whereas several other genes are mostly specific to a single tumour type." (PMID 28585546, 2017). "In support of this notion, ACVR2A and TGFBR2 were also reported by TCGA as the top two representative genes in hypermutated tumours, 77% of which were MSI7." (PMID 27302369, 2016). "Subcutaneous transplantation into C57BL/6 mice yielded no important difference in tumor size between Acvr2a-KO and Acvr2a/Hif1a-KO Hepa1-6 cells." (PMID 40139191, 2025). "Given the observed increase in proteins found in the PI3K/AKT signaling pathway in activin (+) regions of the tumor, we next explored the potential role for activin and the PI3K pathway in transwell migration assays performed on the ACVR2A-expressing HCT116+chr2 cell line." (PMID 37296966, 2023). "Though ACVR2A mutations, reported in several cases of CRC, have been previously linked to earlier tumor stages (stages I/II), TRIB2 correlation to tumor staging was not performed within this study." (PMID 34198908, 2021). "Mice treated with Bu-Cy showed significant increases in activin A receptors, ACVR2A, and ACVR1B, indicating that the state of the tumor microenvironment (such as activin A increase under chemotherapy) could augment activin A responsiveness." (PMID 34440938, 2021). "In37 cases, lymphocytes were present in tumor tissue, while in 47 cases they were not.A lower level of ACVR2A expression was observed in patients withlymphocytic infiltration." (PMID 30856244, 2019). "Since ACVR2A expression is reduced in microsatellite instable CRC, these tumours might benefit from treatment with these drugs." (PMID 29101300, 2017). "In the present study, ACVR2A-KO HCC tissues were enriched with Treg cells and insusceptible to anti-PD-1 therapy, and the combination with the MCT4 inhibitor VB124 could ameliorate the CD8/Foxp-3 ratio and attenuate tumor growth." (PMID 40139191, 2025). "Interestingly, the expression of ACVR2A appeared to decline gradually with the disease progression, with the highest level of expression in the normal skin and the lowest in SCCs in all five GEP data sets, suggesting its potential tumour suppressing role in disease progression." (PMID 30202019, 2018). "Meanwhile, only one of three tumours with TGFBR2, but not ACVR2A, and one of six tumours with the reverse profile were MSI." (PMID 27302369, 2016). "In our syngeneic transplantation model of Acvr2a-KO HCC, treatment with anti-PD-1 antibody could exhibit no inhibitory impacts on tumor growth." (PMID 40139191, 2025). "Moreover, the 60 s kINPen plasma treatment, which reduced absolute lesion and tumor sizes significantly, was the only treatment not showing a reduction in ACVR1B, ACVR2A, CSF1, EGF, EGFR, IL15, and IL6RA when compared to all other treatments in the high dose DBP group." (PMID 34667240, 2021).
cancer (40 papers, 2009 to 2025). A tumor composed of atypical neoplastic, often pleomorphic cells that invade other tissues. "We aimed to clarify the molecular mechanism underlying the activation of glycolysis, hypoxia, and angiogenesis signaling pathways, which play essential functions in cancer progression and immune evasion in ACVR2A-deficient cells." (PMID 40139191, 2025). "Similarly, an analysis of the genomic landscape of MSI-H in 11,395 tumors across 30 cancer types showed that mutations in ACVR2A (73%), KMT2D (68%), KMT2B (66%), and MMR-related genes were enriched in the MSI-H group." (PMID 38281914, 2024). "Indeed, ACVR2A was the most frequently mutated known cancer gene in our MSI SBAs." (PMID 29522538, 2018). "In contrast, activin A (Inhba), one of the main ligands bound by both FST and FSTL3 was primarily secreted by cancer cells, while its type II receptors (Acvr2a, Acvr2b) were highly expressed in both cancer cells and fibroblasts (Log2 FC > 0.5)." (PMID 41029436, 2025). "GSEA was employed to elucidate the effect of ACVR2A gene knockout on critical genes and biological pathways in cellular systems, and the canonical pathways from the Cancer Genome Project (CGP) database were investigated." (PMID 40444773, 2025). "For example, TGFβ–BMP signalling was mostly inactivated by co-SMAD SMAD4 mutations in MSS cancers, but by one or more indel receptor mutations (TGFBR2, ACVR2A, BMPR2 and ACVR1B) in MSI cancers." (PMID 39112709, 2024). "Emerging evidence indicated that ACVR2A is involved in many cancer-related signaling pathways, such as the PEDF-induced signaling, the TFG-β signaling, or signaling pathways regulating stem cell pluripotency." (PMID 35140786, 2022). "This work identified a cluster of co-mutation genes (LRP1, ACVR2A, and SETBP1) and found these genes were significantly associated with a family history of cancer." (PMID 35814400, 2022). "The mechanism responsible for the downregulation of BMPR2 in EBNA1-expressing and EBV-infected carcinoma cells in vitro is unclear, but the fact that these cells showed robust Smad1/5/8 phosphorylation suggests that ACVR2A or ACVR2B can substitute for BMPR2." (PMID 32708289, 2020). "For a completeview of ACVR2A gene expression in different stages of cancerdevelopment it seems advisable to extend the study to include patients withcolorectal cancer to compare ACVR2A expression in each of the T1,T2, T3, and T4 groups separately." (PMID 30856244, 2019). "Patients with mutations in LRP1, ACVR2A, and SETBP1 tend to have a family history of cancer." (PMID 35814400, 2022). "Additionally, evidence from recent studies has shown that cancer development can be affected by mutations in the TGFβII receptor (TGFBR2), SMAD4, and activin receptor 2A (ACVR2A)." (PMID 31906017, 2019). "Some of these genes have shown strong predictive power for MSI-H status (for example, ACVR2A and KIAA2018 for COAD, STAD and UCEC), whereas others display low recurrence for single cancer types (for example, SMAP1 for STAD)." (PMID 28585546, 2017).
cancer (continued). "In some respects, MSS-GS cancers resembled MSI cancers with respect to proximal location, near-diploid genomes and shared driver genes such as TGFBR2, ACVR2A and ARID1A, but there was no increased mutation burden." (PMID 39112709, 2024). "Additionally, TGFBR2, ACVR2A, and SMAD4 were shown to have high alteration frequencies in pan-cancer." (PMID 36968603, 2023). "One gene (ACVR2A) was predicted by both xseq and MuSiC but was not in the bona fide cancer gene list." (PMID 26436532, 2015). "For the positive–negative subjects (screening), 3 CNAs were detected in BC genes (ACVR2A, CUL3 and PIK3R1), and 5 SNPs were identified in 6 non-BC cancer genes (SNIP1, TBC1D10B, PANK1, PRKCA and RUNX2; SUPT3H)." (PMID 35589867, 2022). "The TGF-β pathway was deregulated by alterations to TGFBR1, TGFBR2, ACVR2A, ACVR1B, SMAD2, SMAD3 and SMAD4 in 27 % of non-hypermutated MSS tumours and 87 % of hypermutated cancers." (PMID 27325016, 2016).
metabolic disease (1 paper, 2025). A congenital disorder (due to inherited enzyme abnormality) or acquired (due to failure of a metabolically important organ) disorder resulting from an abnormal metabolic process. "Thus, ACVR2A inactivation in non-viral and metabolic disease-related HCC recruits Treg cells, leading to unfavorable outcome and extrinsic resistance to PD-1 blockade." (PMID 40139191, 2025).
ACVR2A also shares sentences with these, for which no sentence is quoted: pulmonary arterial hypertension (7 papers); osteoporosis (5); pancreatic cancer (5); Cachexia (3); heart failure (3); pulmonary hypertension (3); multiple myeloma (2); myocardial infarction (2); sarcopenia (2); Splenomegaly (2); thalassemia (2); bacterial infections (1); Bardet-Biedl syndrome (1); cardiac hypertrophy (1); cardiomyopathies (1); cardiovascular diseases (1); cartilaginous neoplasms (1); colorectal adenoma (1); fibrodysplasia ossificans progressiva (1); gastric tumors (1); genetic disorders (1); Glucose intolerance (1); GNE myopathy (1); heart disease (1); Hepatic steatosis (1); hypogonadism (1); infection (1); influenza infection (1); injury (1); intestinal cancer (1).
A further 21 diseases each share a sentence with ACVR2A in 1 paper.